EMX1 (empty spiracles homeobox 1)
Diseases named in the same sentence as EMX1 in open-access papers (continued):
Sharing a sentence is not in itself a finding about the gene and the disease.
sarcoma (2 papers, 2021). A usually aggressive malignant neoplasm of the soft tissue or bone. "Our work showed that EMX1/EMX2 act as tumor suppressors in sarcomas by repressing the activity of stem cell regulatory genes (OCT4, SOX2, KLF4, MYC, NANOG, NES, and PROM1)." (PMID 34016958, 2021). "The 3MC carcinogen-induced sarcomas have a more aggressive phenotype, increased infiltration into the femoral bone marrow, and reduced survival in the Emx1/Emx2 KO mice." (PMID 34016958, 2021). "Murine KO models of Emx1 or Emx2 have been used to validate the initiation and development of sarcomagenesis in sarcomas induced with wild or hemizygous levels of Emx1/Emx2." (PMID 34016958, 2021). "Comparing the control muscle tissues and the induced sarcoma, we observed the highest expression of the stem cell genes (Oct4, Sox2, Klf4, Myc, and Nanog) and aggresivity in the sarcomas induced in the Emx1 or Emx2 KO mice." (PMID 34016958, 2021). "The results obtained in our cell model showed a reduction in stem cell characteristics when EMX1 or EMX2 was overexpressed in primary sarcoma cell lines." (PMID 34364391, 2021). "All together, our results suggest that sarcoma self-renewing populations originate from neural or mesodermal precursors where EMX1 and/or EMX2 expression is silenced." (PMID 34016958, 2021). "In this way, the Wnt pathway was established as one of the pathways related to the action of the transcription factors EMX1/EMX2 in sarcoma tumorigenesis." (PMID 34364391, 2021). "In the murine Emx1 model, a reduction in Emx1 levels was obtained in the heterozygous Emx(+/−) mice and no expression was found in the Emx(−/−)-null homozygotes, with lower expression levels in induced sarcoma (T) than in control muscle tissue (C)." (PMID 34016958, 2021). "To explore the role of EMX, we first selected three different low-passage sarcoma cell lines from different tissues of origin; two sarcoma lines expressed low levels of EMX1 and EMX2, as models to study the effects of EMX overexpression: AA (leiomyosarcoma) and AW (liposarcoma)." (PMID 34016958, 2021). "However, many sarcoma cells and tumors still maintain high levels of Emx1/Emx2 protein expression, suggesting the existence of other active pathways that bypass the tumor suppressive roles of EMX1/EMX2 in the initiation and progression of human sarcoma." (PMID 34364391, 2021). "As many sarcomas have their origin in the differentiation of neural crest-derived multipotent cells, certain genes involved in the differentiation of this main embryological feature, such as EMX1/2 genes, may be deregulated in sarcomas." (PMID 34016958, 2021). "To examine whether this effect was observed in sarcoma patients, we analyzed the correlations between the expression of EMX1/EMX2 and the expression of genes in signaling pathways regulating the phenotype of stem cells in thePerlman (N = 53), and head and neck tumors: TGCA (N = 520) datasets." (PMID 34364391, 2021). "In addition, the Emx1/Emx2 KO mice that are induced with sarcoma have decreased survival." (PMID 34016958, 2021). "Taken together, these results indicate that the EMX1 and EMX2 genes negatively regulate these tumor-remodeling populations or sarcoma stem cells, acting as tumor suppressors in sarcoma." (PMID 34364391, 2021). "In this work, we showed that the canonical Wnt pathway is one of the mechanisms that explains the relationships of EMX1/EMX2 and stem cell genes in sarcoma." (PMID 34364391, 2021). "The transcription factors EMX1 and EMX2 act as tumor suppressors in sarcomas in vitro and in vivo by decreasing the expression of genes regulating the properties of stem cells and the stem cell phenotype." (PMID 34016958, 2021). "In summary, our work showed that EMX1 and EMX2 act as tumor suppressors by suppressing the activity of stem cell regulatory genes (OCT4, KLF4, MYC, SOX2, NANOG, NES, and PROM1) in sarcoma." (PMID 34016958, 2021).
sarcoma (continued). "Together, these results indicate that the EMX1 and EMX2 genes negatively regulate these tumor-altering populations or cancer stem cells, acting as tumor suppressors in sarcoma." (PMID 34016958, 2021). "Together with previous works, this study proposes that the expression of EMX1 and EMX2 is maintained in only cancer stem cells embedded in the tissue of origin of the sarcoma to maintain the quiescent state by repressing the Wnt pathway." (PMID 34364391, 2021). "The Wnt-EMX1/EMX2 relationship was validated in silico with sarcoma patient datasets, in vitro in primary derived sarcoma cell lines, and in vivo." (PMID 34364391, 2021). "Hypermethylation of the EMX1 and EMX2 promoters has been demonstrated in primary sarcoma lines." (PMID 34364391, 2021). "However, the role of EMX1/EMX2 in the initiation and progression of human sarcoma, as a tumor model derived from the mesoderm and neural crest, has not yet been elucidated." (PMID 34016958, 2021). "Therefore, we proceeded to characterize the activation state of the canonical Wnt pathway in primary sarcoma lines, including both EMX1 and EMX2 overexpression in AA and AW models and EMX1/EMX2 silencing in a BG model." (PMID 34364391, 2021). "In summary, our work shows that EMX1 and EMX2 act as tumor suppressors by suppressing the activity of stem cell regulatory genes (OSKM, NANOG, and PROM1) and effectors of the canonical Wnt pathway (CTNNB1, TCF4, MYC, WNT1 and CCDN1) in sarcoma." (PMID 34364391, 2021). "It is proposed that there is no or low expression of EMX1 and EMX2 in CSCs embedded in the tissue of origin of the sarcoma, allowing self-renewal of the tumor." (PMID 34016958, 2021).
Alazami syndrome (1 paper, 2024). "Building upon these findings, we use Emx1-Cre and nestin-Cre to knock out Larp7, a gene linked to a human NDD called Alazami syndrome (OMIM, # 615071)." (PMID 39479517, 2024). "Furthermore, we use Emx1-Cre and nestin-Cre to knock out Larp7, a gene linked to a human NDD called Alazami syndrome." (PMID 39479517, 2024).
Ataxia (1 paper, 2023). Ataxia refers to impaired coordination of voluntary muscle movement. "The results of a panel of motor tests including the rotarod test, the hangwire test and footprint analysis confirmed that Emx1-Cre::Lrp1fl/fl knock-out mice suffered from cortically induced ataxia." (PMID 37383546, 2023). "The cortical circuitry resulting in ataxia in the Emx1-Cre::Lrp1fl/fl line has not been elucidated in detail." (PMID 37383546, 2023).
brain injury (1 paper, 2016). Acute and chronic (see also brain INJURIES, CHRONIC) injuries to the brain, including the cerebral hemispheres, CEREBELLUM, and brain STEM. "This suggests that brain injury and behavioral training elicit more growth promoting signals aside from VEGF that are conducive for neurogenesis in the Emx1 KO mice." (PMID 27799894, 2016).
brain malformations (1 paper, 2018). "Since Emx1-fukutin-cKO and Largemyd/myd mice demonstrated diffuse and severe brain malformations at E18.5, respectively, these two strains were used for rescue experiments." (PMID 29360985, 2018).
cerebral palsy (1 paper, 2016). A group of disorders affecting the development of movement and posture, often accompanied by disturbances of sensation, perception, cognition, and behavior. "The Emx1-Cre:EphA4tm2Kldr mouse shares features with the common developmental disorder cerebral palsy: bilateral voluntary motor impairments and bilateral CST miswiring." (PMID 27673329, 2016).
cognitive (1 paper, 2022). "Finally, since impairment of motor control and learning have been reported in children with ASD, we checked Emx1-cKO and Chat-cKO mice for motor and cognitive deficits." (PMID 35292625, 2022).
fibrosarcoma (1 paper, 2021). A malignant mesenchymal fibroblastic neoplasm affecting the soft tissue and bone. "We also selected a third line, with high expression of EMX1 and EMX2 (BG, mixoid fibrosarcoma) as the model to reduce the levels of both genes." (PMID 34016958, 2021).
glioma (1 paper, 2022). A benign or malignant brain and spinal cord tumor that arises from glial cells (astrocytes, oligodendrocytes, ependymal cells). "EMX1 was poorly expressed in glioma, which was linked to decreased survival rate of patients according to the bioinformatics prediction." (PMID 35849030, 2022). "Data in the bioinformatics system showed that the expression of EMX1 was significantly reduced in glioma, and patients with high EMX1 expression had greater overall survival rate than those with low EMX1 expression." (PMID 35849030, 2022). "Empty spiracles homobox genes (EMXs) have shown potential tumor suppressing roles in glioma, but the biological function of EMX1 in SCG is unclear." (PMID 35849030, 2022). "However, the role of EMX1 in glioma, especially in SCG, remains unarticulated." (PMID 35849030, 2022).
hepatobiliary tumors (1 paper, 2023). "Remarkably, EMX1 was recognized recently as a potential clinically available epi-marker in hepatobiliary tumors, but with undefined mechanism and function in HCC." (PMID 38007497, 2023). "In this set of genes, we focused on the hypermethylation of EMX1, which is frequently observed in hepatobiliary tumors." (PMID 38007497, 2023). "Despite a few studies focused on EMX1 DNA hypermethylation in hepatobiliary tumors recently, its underlying mechanisms have not yet been elucidated." (PMID 38007497, 2023).
Hydrocephalus (1 paper, 2016). Hydrocephalus is an active distension of the ventricular system of the brain resulting from inadequate passage of CSF from its point of production within the cerebral ventricles to its point of absorption into the systemic circulation. "To eliminate the possibility that a mechanism independent of the aqueduct induces non-communicating hydrocephalus, we deleted Yap in other parts of the neuroepithelium by Emx1 Cre (expressed only in dorsal cortex) and hGFAP Cre (radial glia progenitors but not in the ventral midbrain)." (PMID 26754915, 2016).
ischemic stroke (1 paper, 2016). A stroke disorder caused by obstruction of blood flow to the brain, due to thrombotic (local blood clot formation) or embolic (due to a blood clot or other material traveling from another site) event. "Despite the impaired VEGF signaling and reduced neurogenesis in the Emx1 KO mice, ischemic stroke with distal occlusion of the middle cerebral artery did not induce a greater lesion size in the KO compared to the WT mice, neither did traumatic brain injury (TBI) (unpublished results)." (PMID 27799894, 2016).
Tremor (1 paper, 2014). An unintentional, oscillating to-and-fro muscle movement about a joint axis. "The Emx1-Xpg mice did not develop tremors and deficits in accelerating rotarod performance." (PMID 25299392, 2014).
cancer (8 papers, 2019 to 2025). A tumor composed of atypical neoplastic, often pleomorphic cells that invade other tissues. "In PCa, the sensitivity and specificity for cancer detection were 100% and 91.7% for EMX1, 78.6% and 91.7% for Chr5q14.1, 57.1%, and 91.7% for NXPH1, and reached 100% and 87.5% for the combined triplex methylation score." (PMID 41008642, 2025). "Nonetheless, further studies are required to unravel the EMX1 splicing regulators and the distinct isoforms in cancers, linking the potential relationship between gene body methylation, RNA splicing, and the roles played by EMX1 isoforms." (PMID 38007497, 2023). "The relationship between miR-497/EMX1 and cancer needs further study." (PMID 31481972, 2019). "However, the biological function and detailed molecular mechanism of EMX1 in cancer remain unclear." (PMID 38007497, 2023). "We first identified reduced EMX1 in SCG tissues and the isolated cells, especially in the high‐grade cancers." (PMID 35849030, 2022). "EMX1/EMX2 reduce the activation of the Wnt pathway, properties of cancer stem cells, and expression of genes that regulate stemness." (PMID 34364391, 2021). "MSigDB Collection (c6.all.v6.2.symbols.gmt), which represents signatures of cellular pathways often dysregulated in cancer, was applied to our GSEA analysis at the phenotype of EMX1 expression level." (PMID 31481972, 2019). "The EMX1 and EMX2’s potential as tumor suppressor genes has been suggested in some cancers." (PMID 34016958, 2021).
tumor (7 papers, 2019 to 2024). "Both low expression of miR-497 and overexpression of EMX1 were significantly associated with more advanced clinicopathologic characteristics (stage, tumor status, grade, and histology) besides survival (all P values < 0.05)." (PMID 31481972, 2019). "The results from sixty paired samples showed that both of these two EMX1 transcripts were highly expressed in HCC tumor tissue compared to ANLT, and displayed a high similarity of expression patterns (r = 0.95, P < 0.0001)." (PMID 38007497, 2023). "After analyzing BSP sequencing results, we noticed positive correlations between EMX1 gene body methylation and mRNA expression following R2 (r = 0.80, P < 0.01), R4 (r = 0.70, P = 0.01) and R3 (r = 0.52, P = 0.08) in tumor." (PMID 38007497, 2023). "These suggest that EMX1 potentially exhibits both oncogenic and tumor-suppressive activities in a context-dependent manner." (PMID 38007497, 2023). "Further confirmation was done through 3’RACE sequencing in HCC tumor tissue cDNA, where it was found that EMX1 mRNA 3’ end had a consensual 562-bp-long terminal exon and a shorter alternative terminal exon (546 bp)." (PMID 38007497, 2023). "The findings above suggested that restoration of WASF2 blocked the tumor‐suppressing role of EMX1 in SCG." (PMID 35849030, 2022). "Poor expression of EMX1 was identified in the SCG tissue samples, and the expression was further decreased as the tumor grade increases, indicating the potential involvement of EMX1 downregulation in the development of SCG." (PMID 35849030, 2022). "Overexpression of EMX1 significantly slowed down the growth rate of xenograft tumors in mice and reduced the tumor weight." (PMID 35849030, 2022). "This study elucidates that EMX1 functions as a tumor inhibitor in SCG by suppressing WASF2‐dependent activation of the Wnt/β‐catenin axis." (PMID 35849030, 2022). "How does activation of the canonical Wnt pathway affect the tumor suppressor activity of the EMX1/EMX2 genes?" (PMID 34364391, 2021). "Moreover, EMX1 overexpression also significantly reduced the size of tumor cell infiltration in mouse lung tissues in the setting of tail vein injection." (PMID 35849030, 2022). "Restoration of WASF2 blocked the tumor‐suppressing effect of EMX1." (PMID 35849030, 2022). "Therefore, the tumor-suppressive effect of the EMX1/EMX2 genes measured in terms of the proliferative rate and clone formation is lost when mutant CTNNB1 is overexpressed." (PMID 34364391, 2021). "In addition, it was found that coexpression of mutant CTNNB1 with EMX1 or EMX2 individually or both EMX genes (EMX1 + EMX2) enabled reversion to a more aggressive tumor phenotype due to increased cell proliferation and clonogenicity." (PMID 34364391, 2021). "Functional proliferation, clone formation, and tumor formation tests and measurement of the expression levels of genes related to stem cell biology were performed to evaluate the effect of the constitutively active Wnt pathway on the individual or combined overexpression of the EMX1/EMX2 genes." (PMID 34364391, 2021). "In tumors with sarcomatoid transformation, high expression of EMX1 and EMX2 reveals reverberant pathways that override the tumor suppressive role during the local progression of all tumor types." (PMID 39337467, 2024). "Mechanistically, EMX1-FL bound to EGFR promoter, promoting EGFR transcription and activating EGFR-ERK signaling to trigger tumor metastasis." (PMID 38007497, 2023). "Compared to normal samples, the expression of E2F2, FOXJ1, EMX1, PAX7, NKX6-1, FOXD1, and ZNF552 was significantly higher (P < 0.05) and the expression of MSX1, STAT4, NR3C2, and EGR3 was significantly lower in tumor samples (all P < 0.05)." (PMID 33688372, 2021). "They highlighted that EMX1 and EMX2 act as tumor suppressors by restraining the effector of the canonical WNT pathway, though the precise molecular mechanism remained unknown." (PMID 38007497, 2023).
tumor (continued). "The results indicated a reduction in the number, size, and efficiency of tumor formation, as well as a negative correlation of the CD133+ fraction with the EMX1 and EMX2 levels." (PMID 34016958, 2021).
genetic diseases (1 paper, 2022). "Thus, even when the phenotype of an Emx1-IRES-Cre-based mutant mouse recapitulates a specific genetic disease, the phenotype cannot be solely attributed to forebrain excitatory neurons if the gene of interest is also expressed in peripheral sites." (PMID 36192157, 2022).
infection (1 paper, 2022). The state of being infected such as from the introduction of a foreign agent such as serum, vaccine, antigenic substance or organism. "We expressed ChR2 in mPFC neurons by injecting AAV-EF1α-DIO-ChR2-EYFP and the retrograde tracer AAV-retro-tdTomato into the mPFC of Emx1-Cre mice, to prevent possible retrograde infection to AM neurons." (PMID 35296648, 2022).
EMX1 also shares sentences with these, for which no sentence is quoted: neurodevelopmental disorder (3 papers); Intellectual disability (2); neurologic diseases (2); absence seizures (1); acute myeloid leukemia (1); Anosmia (1); brain glioma (1); breast carcinoma (1); Cachexia (1); craniorachischisis (1); dystroglycanopathy (1); endometrial cancer (1); head and neck tumors (1); hearing loss (1); infertility disorder (1); invasive breast carcinoma (1); leiomyosarcoma (1); leukemia (1); liposarcoma (1); liver cancer (1); memory impairment (1); neuroendocrine carcinoma (1); osteosarcoma (1); pancreatic carcinoma (1); Parkinson disease (1); pituitary stalk interruption syndrome (1); primary sclerosing cholangitis (1); renal failure (1); Sandhoff disease (1); spinal cord glioma (1).
A further 4 diseases each share a sentence with EMX1 in 1 paper.